RPS26 (ribosomal protein S26)
Description:
Component of the small ribosomal subunit. The ribosome is a large ribonucleoprotein complex responsible for the synthesis of proteins in the cell.
Synonyms: S26; eS26; DBA10
Tractability: Small molecule: an approved drug acts on it; a structure with a bound ligand is known; a high-quality ligand is known. PROTAC: ubiquitination databases record sites on it; its protein half-life has been measured; a small molecule that binds it is known. Other modalities: a drug acting on it is in phase 2 or 3 trials.
Gene: Protein-coding gene on chromosome 12 (56,041,351 to 56,044,697, forward strand). Ensembl gene ENSG00000197728.
Subcellular location: Cytoplasm, cytosol; Cytoplasm; Rough endoplasmic reticulum
Subcellular location (Human Protein Atlas): Cytosol; Endoplasmic reticulum; Nucleoli
Pathways (Reactome):
Metabolism of proteins: Eukaryotic Translation Termination; Formation of a pool of free 40S subunits; Formation of the ternary complex, and subsequently, the 43S complex; GTP hydrolysis and joining of the 60S ribosomal subunit; L13a-mediated translational silencing of Ceruloplasmin expression; PELO:HBS1L and ABCE1 dissociate a ribosome on a non-stop mRNA; Peptide chain elongation; Ribosomal scanning and start codon recognition; SRP-dependent cotranslational protein targeting to membrane; Translation initiation complex formation; ZNF598 and the Ribosome-associated Quality Trigger (RQT) complex dissociate a ribosome stalled on a no-go mRNA
Disease: SARS-CoV-1 modulates host translation machinery; SARS-CoV-2 modulates host translation machinery; Viral mRNA Translation
Metabolism of RNA: Major pathway of rRNA processing in the nucleolus and cytosol; Nonsense Mediated Decay (NMD) enhanced by the Exon Junction Complex (EJC); Nonsense Mediated Decay (NMD) independent of the Exon Junction Complex (EJC)
Cellular responses to stimuli: Response of EIF2AK4 (GCN2) to amino acid deficiency
Developmental Biology: Regulation of expression of SLITs and ROBOs
Metabolism: Selenocysteine synthesis
Gene Ontology:
Molecular function: cadherin binding; mRNA binding; protein binding; RNA binding; structural constituent of ribosome
Biological process: cytoplasmic translation; negative regulation of RNA splicing; translation
Cellular component: cytosol; cytosolic small ribosomal subunit; endoplasmic reticulum; extracellular exosome; membrane; nucleolus; ribosome; small ribosomal subunit; cytoplasm; cytoplasmic side of rough endoplasmic reticulum membrane; nucleoplasm; rough endoplasmic reticulum; cytosolic ribosome
Genetic constraint (gnomAD): Loss-of-function variants: 1 observed, 14.85 expected, observed/expected ratio (o/e) 0.0674, 90% interval 0.023 to 0.32. The upper end of that interval is the gene's LOEUF score, 0.32, which puts it in group 1 of 6, group 1 being the genes least tolerant of losing a copy. Missense variants: 63 observed, 157.01 expected, observed/expected ratio (o/e) 0.4, 90% interval 0.33 to 0.5. Synonymous variants: 59 observed, 54.1 expected, observed/expected ratio (o/e) 1.09, 90% interval 0.88 to 1.35.
Homologues: Orthologues: chimpanzee RPS26 (100% identical), rat Rps26l6 (99% identical), rabbit RPS26 (97% identical), zebrafish rps26l (97% identical), zebrafish rps26 (97% identical), tropical clawed frog rps26 (94% identical), Drosophila melanogaster RpS26 (77% identical), Caenorhabditis elegans rps-26 (76% identical).